MIR548D1 (microRNA 548d-1)
Synonyms: hsa-mir-548d-1; MIRN548D1
Gene: MicroRNA gene on chromosome 8 (123,348,034 to 123,348,130, reverse strand). Ensembl gene ENSG00000283172.
Diseases named in the same sentence as MIR548D1 in open-access papers:
MIR548D1 is named in the same sentence as 1 disease in open-access papers, as found by Europe PMC text mining. Sharing a sentence is not in itself a finding about the gene and the disease.
MIR548D1 shares sentences with these, for which no sentence is quoted: breast carcinoma (1 paper).